ELOA3BP (elongin A3 family member B, pseudogene)
Synonyms: HsT828; ELOA3; ELOA3B; ELOA3CP; ELOA3L1; EloA3C; Elongin-A3; TCEB3C; TCEB3CL; TCEB3L2; eloA3-like-1
Gene: Processed pseudogene on chromosome 18 (47,022,287 to 47,023,927, reverse strand). Ensembl gene ENSG00000288607.
Diseases named in the same sentence as ELOA3BP in open-access papers:
ELOA3BP is named in the same sentence as 2 diseases in open-access papers, as found by Europe PMC text mining. Sharing a sentence is not in itself a finding about the gene and the disease.
ELOA3BP shares sentences with these, for which no sentence is quoted: amyotrophic lateral sclerosis (1 paper); meningioma (1).